RNU6-1100P (RNA, U6 small nuclear 1100, pseudogene)
Gene: Small nuclear RNA gene on chromosome 1 (157,784 to 157,887, reverse strand). Ensembl gene ENSG00000222623.
Homologues: Orthologues: macaque U6 (91% identical), pig U6 (84% identical), pig U6 (78% identical), dog U6 (77% identical). Paralogues in human: RNU6-1076P (100% identical), RNU6-1118P (100% identical), RNU6-1217P (100% identical), RNU6-355P (100% identical), RNU6-447P (100% identical), RNU6-785P (100% identical), RNU6-791P (100% identical), RNU6-860P (100% identical), U6 (100% identical), RNU6-1054P (99% identical), RNU6-1199P (99% identical), RNU6-1319P (99% identical), and 1289 more.